CTBP1 (C-terminal binding protein 1)
Diseases named in the same sentence as CTBP1 in open-access papers (continued):
Sharing a sentence is not in itself a finding about the gene and the disease.
infection (10 papers, 2010 to 2024). The state of being infected such as from the introduction of a foreign agent such as serum, vaccine, antigenic substance or organism. "We noted that there was a higher level of WNV replication in the patient-derived CTBP1 p.R342W neuronal cells as compared to healthy control neurons from 4 h post infection until the end of the assay." (PMID 33192249, 2020). "We interpret these results to mean that the CTBP1 p.R342W neurons might be more susceptible to WNV infection as the virus replicated to higher titers in mutant neurons compared to control neurons for most of the time points tested (about 100-fold at 20 h after infection)." (PMID 33192249, 2020). "During early HIV invasion of the brain and interaction with the blood–brain barrier, there is a regulatory role for CtBP1 nuclear translocation by the brain pericyte tight junction protein occludin, with occludin levels decreasing by approximately 10% within 48h post-infection." (PMID 38932279, 2024). "The effect of CTBP1 p.R342W on interferon-response genes was unexpected since patients have not demonstrated any increased susceptibility toward infections although this has not been characterized in detail." (PMID 33192249, 2020). "We also determined the effects of endogenous CtBP1 and CtBP2 on the E2F1 promoter activity by using A549 cells that were acutely depleted of both CtBP1 and CtBP2 by infection with lentiviral vectors that express shRNAs against CtBP1 and CtBP2 followed by short term drug selection." (PMID 24955216, 2014). "Within the infection pathway, HAdV3 was found in macropinosomes that also contained the CD46, αv integrins, and the C-terminal binding protein 1 of E1A (CtBP1)." (PMID 34683878, 2021). "The authors also observed that infection of hematopoietic cells with HAdV5 was independent of CtBP1 but sensitive to clathrin siRNA, further confirming that HAdVs of different serotypes can infect the same cells in a different manner, not only receptor wise but also endocytosis wise." (PMID 34683878, 2021).
neurodevelopmental disorder (4 papers, 2020 to 2026). A behavioral and cognitive disorder with onset during the developmental period that involves impaired or aberrant development of intellectual, motor, or social functions. "We present a novel case of CTBP1-related neurodevelopmental disorder and demonstrate, for the first time, the application of non-invasive, real-time mitochondrial functional assessment in this setting, providing additional evidence for mitochondrial dysfunction in HADDTS." (PMID 42123581, 2026). "Our case contributes to the evidence that secondary mitochondrial dysfunction may contribute to the pathogenesis in the CTBP1‐related neurodevelopmental disorder." (PMID 36341169, 2022).
mitochondrial disease (2 papers, 2022 to 2024). "Although CTBP1 variants can lead to mitochondrial complex I and IV activities impairments in skeletal muscle, causing mitochondrial diseases, the patient we described did not exhibit any biochemical changes or muscle abnormalities." (PMID 38348454, 2024). "It remains to be determined whether this patient will gradually manifest phenotypes of both mitochondrial disease and HADDTS as she ages or if this variant in CTBP1 will result in another disease or subtype alternatively, these symptoms may represent heterogeneous manifestations of HADDTS." (PMID 38348454, 2024).
movement disorder (1 paper, 2020). Neurological conditions resulting in abnormal voluntary or involuntary movement, which may impact the speed, fluency, quality and ease of movement. "The altered gene expression profiles appear to be consistent with intellectual and movement disorder phenotypes seen in patients with CTBP1 mutations." (PMID 33192249, 2020).
CTBP1 also shares sentences with these, for which no sentence is quoted: Hypotonia (6 papers); gastric cancer (5); adenocarcinoma (4); Intellectual disability (3); leukemia (3); adenovirus infection (2); Familial adenomatous polyposis (2); hypotonia, ataxia, developmental delay, and tooth enamel defect syndrome (2); intestinal polyposis (2); lung adenocarcinoma (2); lymphoma (2); metastatic prostate carcinoma (2); polyposis (2); thyroid cancer (2); triple-negative breast carcinoma (2); acute pancreatitis (1); angiosarcoma (1); bladder cancers (1); clear cell renal cell carcinoma (1); colitis (1); colon adenocarcinoma (1); congenital heart disease (1); esophageal cancer (1); Failure to thrive (1); Fanconi anemia (1); glioma (1); gout (1); heart failure (1); hematologic cancers (1); Hip dysplasia (1).
A further 25 diseases each share a sentence with CTBP1 in 1 paper.